ROS1 (ROS proto-oncogene 1, receptor tyrosine kinase)
Diseases named in the same sentence as ROS1 in open-access papers (continued):
Sharing a sentence is not in itself a finding about the gene and the disease.
lung adenocarcinoma (continued). "Currently, approximately 60% of lung adenocarcinomas have now been shown to have mutations (KIF5B-Ret, ROS1, NTRK1, HER2-Neu, to name a few) that may induce and drive these malignancies and the association of TTF-1 status and presence of these driver mutations remains to be elucidated." (PMID 25594059, 2014). "The top five actionable alterations in lung adenocarcinomas were reported in EGFR (43 %), ALK (5 %), BRAF (5 %), KRAS (5 %), and ROS1 (2 %) genes." (PMID 40821453, 2025). "The aim of this study is to detect fusion transcripts in the ALK, RET, ROS1, and NTRK1 genes through next‐generation RNA‐seq on samples obtained from paraffin‐embedded tissue, liquid biopsy, and EBC from 30 lung adenocarcinoma patients undergoing treatment." (PMID 39810398, 2025). "We conducted a retrospective study of patients with advanced lung adenocarcinoma harboring ALK, ROS1, and RET fusions, comparing them with cohorts harboring EGFR mutations." (PMID 40751559, 2025). "Targeted therapies directed at fusion proteins resulting from ALK, ROS1, RET, and other gene fusions underscore the importance of routinely identifying these alterations in patients with lung adenocarcinoma." (PMID 39810398, 2025). "The increasing use of targeted therapies for ALK, ROS1, and RET gene rearrangements has underscored the critical importance of routine genetic screening in patients with lung adenocarcinoma." (PMID 39810398, 2025). "During the study, 2343 patients with advanced lung adenocarcinoma were diagnosed, including 1167 EGFR+, 327 ALK+, 98 ROS1+, and 56 RET+ patients." (PMID 40751559, 2025). "For example, the G2032R mutation in the ROS1 kinase domain confers resistance to Crizotinib in lung adenocarcinoma (LADC) by disrupting its inhibition of ALK, ROS1, and MET tyrosine kinases." (PMID 40342734, 2025). "Thus, calcified lesions may be characteristic of lung adenocarcinomas with ROS1 fusion." (PMID 39391406, 2024). "Recent Asian expert consensus has reported that the percentage of EGFR alterations in lung adenocarcinoma is higher among East Asian compared to Western population (40–55% vs. 12–25%), while KRAS, BRAF, and ROS1 are lower, with HER2 and MET are nearly similar." (PMID 38245692, 2024). "Patients with newly diagnosed lung adenocarcinoma commonly undergo sequential molecular testing (for EGFR, ALK, ROS1)." (PMID 34918209, 2021). "EML4/ALK fusion-positive lung adenocarcinoma was predicted to be borderline more sensitive to Alectinib (p = 0.0632) and EML4/ALK or ROS1 fusion-positive lung adenocarcinoma was predicted to be more sensitive to Crizotinib (p = 0.044)." (PMID 34548481, 2021). "Somatic mutations in EGFR and KRAS as well as chromosome rearrangements affecting ALK, ROS1, and RET have been identified in human lung adenocarcinoma (LUAD)." (PMID 33348616, 2020). "As far as we know, this study is the first study to compare the efficacy of pemetrexed-based chemotherapy between HER2-mutant and groups of EGFR-mutant, ALK/ROS1-rearranged and KRAS-mutant lung adenocarcinoma." (PMID 29587667, 2018). "The advent of therapies targeting the fusion proteins arising from ALK, ROS1, and RET gene fusions makes the routine detection of these events important in patients with lung adenocarcinoma." (PMID 30115026, 2018). "This is analogous to adenocarcinoma of the lung where fusion genes involving MET, ROS1, and ALK are all treated with TKIs that are effective against each of the kinase domains." (PMID 29654269, 2018). "In lung adenocarcinoma, rearranged genes, including ALK, ROS1, RET, NTRK1, and NRG1, have been reported." (PMID 28894699, 2017). "In lung adenocarcinoma, fusions of ALK, RET, and ROS1 have been shown to be targetable genetic alterations." (PMID 28894699, 2017). "NSCLC patients harboring rearrangements within the ALK, ROS1 and RET gene can be targeted in lung adenocarcinoma using specific therapies such as Crizotinib." (PMID 28404952, 2017).
lung adenocarcinoma (continued). "Previously, we screened for ALK, ROS1, and RET fusion genes in 795 lung adenocarcinoma specimens and identified the novel KIAA1217-RET fusion gene containing KIAA1217 exon 11 and RET exon 11 from a patient with a 4-cm tumor mass (red arrow)." (PMID 27150058, 2016). "Current international guidelines recommend analysis of the following seven genes before starting palliative intent therapy for lung adenocarcinoma: KRAS, EGFR, ALK, ROS1, HER2, BRAF, RET." (PMID 26018876, 2015). "Here, we review advances in targeted treatment of lung adenocarcinoma with respect to five clinically relevant biomarkers – EGFR, ALK, MET, ROS-1, and KRAS." (PMID 25157335, 2014). "Notably, ROS1 and RET rearrangements occur in approximately 1% and 2% of lung adenocarcinoma cases, respectively." (PMID 39810398, 2025). "As for the other reference genes such as ROS1, HER2, RET, MET, NTRK1, NTRK2, and NTRK3, our study did not identify mutations in these genes in patients with lung adenocarcinoma." (PMID 38828424, 2024). "In this report, we present a case of lung adenocarcinoma lacking known cancer driver genes, which developed a ROS1 rearrangement after multiple cycles of pembrolizumab treatment and subsequently responded partially to entrectinib." (PMID 39723367, 2024). "Patient#A was a 69-year-old male, former smoker, treated for a lung adenocarcinoma TTF1+ without EGFR, KRAS, or BRAF mutation or ALK or ROS1 translocation but an expression of 100% of PDL1 on the tumor cell." (PMID 37370798, 2023). "Patient#B was a 53-year-old male, current smoker, with a lung adenocarcinoma TTF1+ PDL1 0% without EGFR, KRAS, or BRAF mutation or ALK and ROS1 translocation but STK11 mutation." (PMID 37370798, 2023). "In conclusion, this study suggests that EGFR mutations were more likely to occur in non‐smoking, stage III–IV, and female patients with lung adenocarcinoma, whereas ALK&ROS1 gene rearrangements were more likely to occur in young patients with lung adenocarcinoma." (PMID 35081265, 2022). "Although neuroendocrine transformation has been widely observed in EGFRm lung adenocarcinomas, it is not unique, and has been observed in patients with driver mutations in ALK and ROS1." (PMID 35268520, 2022). "A small subset of IMT that are negative for ALK rearrangement harbor alternative ROS1 fusions (as can occur in lung adenocarcinomas) and are positive for ROS1 immunohistochemistry." (PMID 33921435, 2021). "Similar to ALK and ROS proto-oncogene 1 (ROS1) fusions, RET fusion is likely to be specific to lung adenocarcinoma, and mainly detected in young female and/or never/light-smoking patients which is similar to ROS1 fusion." (PMID 32587276, 2020). "ROS1 rearrangement with an incidence of 4% of lung adenocarcinoma which are EGFR and ALK negative represents an important targetable driver mutation in the Indian population." (PMID 30915158, 2019). "ROS1 rearrangement with an incidence of 4% of lung adenocarcinoma which is EGFR and ALK negative represents an important targetable driver mutation in the Indian population." (PMID 30915158, 2019). "ROS1 rearrangements constitute a small subset of advanced NSCLC patients (1–3% of lung adenocarcinomas) and are more common in light smokers or never smokers." (PMID 29914100, 2018). "In conclusion, putative lung adenocarcinoma presenting as CUP may involve ROS1 rearrangement, and ROS1 inhibitor therapy may be effective." (PMID 30443294, 2018). "We tested the prediction model on additional cohort of 57 lung adenocarcinoma including 4 ROS1+ and 53 ROS1 IHC 1–3+ but FISH negative cases." (PMID 27648828, 2016). "Fusions of the tyrosine kinase genes ALK (anaplastic lymphoma kinase), ROS1 (c-ros oncogene 1), or RET (rearranged during transfection) occur in 1%–5% of lung adenocarcinomas (LADCs) and their products constitute therapeutic targets for kinase inhibitory drugs." (PMID 26437441, 2015).
lung adenocarcinoma (continued). "In this study, we evaluated the status of driver gene mutations in lung adenocarcinoma samples from 198 East Asian female never-smokers using the MassARRAY® LungCarta Panel and ALK, ROS1, and RET fusion assays." (PMID 25760072, 2015). "Structure of breakpoint junctions for ALK, ROS1, and RET reciprocal fusions in lung adenocarcinoma." (PMID 26437441, 2015). "NTRK-1 fusions have been identified in 3 of 91 lung adenocarcinoma samples that were EGFR/KRAS/ALK-1/ROS-1 negative." (PMID 25505733, 2014). "The present report describes the case of a patient with advanced lung adenocarcinoma, who was identified to be negative for ROS-1 rearrangements by FISH, but positive by immunohistochemistry (IHC)." (PMID 25364439, 2014). "The present study reports the case of a patient with advanced lung adenocarcinoma who was ROS1-positive by IHC, but negative by FISH; the patient was determined to have had a partial response to crizotinib." (PMID 25364439, 2014). "Finally, the TCGA lung adenocarcinoma (LUAD) database was consulted to study the expression of ACE2 in EGFR- and KRAS-mutant samples and ACE2 expression was correlated with EGFR/HER, RAS, BRAF, ROS1, ALK, and MET mRNA expression." (PMID 36077610, 2022). "In multivariate analysis adjusted for age, sex, smoking history, stage, surgical mode, and visceral pleural invasion, the CTNNB1 mutation and fusion genes (ALK, ROS1, RET) were negative prognostic factors for recurrence in early-stage lung adenocarcinoma (HR 4.47, p = 0.001; HR 2.73, p = 0.009)." (PMID 33140254, 2021). "However, to our knowledge, there is no case report of a putative lung adenocarcinoma with ROS1 rearrangement treated with ROS1 inhibitor therapy." (PMID 30443294, 2018). "In addition, ROS1‐rearranged lung adenocarcinomas are more common in younger female nonsmokers." (PMID 40028792, 2025). "CT-guided biopsy confirmed stage IV lung adenocarcinoma (TTF-1 and Napsin A positive, PD-L1 TPS 80%, EGFR/ALK/ROS1 negative)." (PMID 42022515, 2026). "A 73-year-old male patient was diagnosed with left lung adenocarcinoma T3N3M1b stage IVa, EGFR, ALK, ROS1 negative, PDL1 1–49%." (PMID 34521373, 2021). "Certain clinical and imaging features derived from ALK/ROS1/RET fusion-positive lung adenocarcinoma patients were found to be good discriminators of fusion-positive and fusion- negative lung adenocarcinomas." (PMID 34164563, 2021). "A 73-year-old male patient was diagnosed with left lung adenocarcinoma IVa, EGFR, ALK, ROS1 negative." (PMID 34521373, 2021). "We report a 71 year-old male patient diagnosed with advanced lung adenocarcinoma lacking key driving genes (EGFR, ALK, and ROS-1), and low expression of PD-L1 on tumor cells (10-15%)." (PMID 34993345, 2021). "The remaining 2 lung-specific DCB genes (ROS1, BPIFA1) were also increased in the plasma of patients with lung adenocarcinoma, though it did not rise to the level of statistical significance." (PMID 33883548, 2021). "We discovered that 1% of lung adenocarcinomas from East Asian never-smoker female patients harbored gene rearrangements of ROS1 and RET, which have recently been recognized as driver genes in lung adenocarcinoma but had not been evaluated in East Asian female never-smokers." (PMID 25760072, 2015). "However, another ROS1 fusion protein, FIG-ROS1, which is found in human glioblastoma, cholangiocarcinoma and lung adenocarcinoma, showed no dimerization properties, instead existing as a monomer in the fusion protein despite retaining the coiled-coil domains and a leucine zipper." (PMID 23418494, 2013).
glioblastoma (44 papers, 2011 to 2026). The most malignant astrocytic tumor (WHO grade IV). "Glioblastoma was the second most common ROS1+ fusion tumors with an incidence of 6.9% (18/259) in this pan-tumor survey." (PMID 37853341, 2023). "While rare, ROS1 rearrangements have also been reported in gastric cancers, glioblastomas, cholangiocarcinomas, ovarian cancers, colorectal cancers, inflammatory myofibroblastic tumors, angiosarcomas, and epithelial hemangioendotheliomas." (PMID 35233056, 2022). "It was observed that circENTPD7 was upregulated in glioblastoma and targeted ROS1 to increase the proliferation of tumors." (PMID 35993557, 2022). "Chromosomal rearrangements involving ROS1 were first identified in glioblastoma cell line U118MG, with the 3′ region of ROS1 fused to the 5′ region of the FIG gene." (PMID 34884672, 2021). "In collection, these findings indicated that circENTPD7/miR-101-3p/ROS1 signaling pathway provided a new perspective for the treatment of glioblastoma." (PMID 32308563, 2020). "We found that ROS1 was increased in glioblastoma, knockdown ROS1 inhibited cell proliferation and motility." (PMID 32308563, 2020). "This research characterized the regulation of circENTPD7/miR-101-3p/ROS1 axis and its role in glioblastoma." (PMID 32308563, 2020). "ROS1 gene rearrangement, originally described in glioblastomas (FIG‐ROS1), is reported at 2% in NSCLC and up to 3.3% in LUAC." (PMID 32871626, 2020). "ROS1 has shown tumorigenic potential in vitro and in vivo, with glioblastoma the first human cancer shown to harbour ROS1 rearrangements." (PMID 33172113, 2020). "We here provide evidence that miR-101-3p can inhibit glioblastoma pathogenesis by sponging circPENTPD7 and ROS1." (PMID 32308563, 2020). "DS-6051b also has antitumor activity in glioblastoma cell lines harboring a ROS1 fusion, and in human colorectal cancer cell lines harboring a NTRK1 fusion." (PMID 29805770, 2018). "ROS1 oncogenic activation has been observed in patients with different tumor types such as glioblastoma, NSCLC, cholangiocarcinoma, gastric, ovarian and colon carcinoma, angiosarcoma and inflammatory myofibroblastic tumors (IMT)." (PMID 25691052, 2015). "ROS1 was found to be expressed in most glioblastoma cell lines, and characterization of ROS1 cDNA revealed a structural class of transmembrane protein kinase." (PMID 26366867, 2015). "ROS1 rearrangement was first described in 2003 in a glioblastoma cell line and later identified in a non-small cell lung cancer (NSCLC) cell line." (PMID 25691052, 2015). "Rearrangement of ROS1 gene, involving ROS1 carboxy-terminal kinase fused to the amino-terminal portion of a protein called FIG (Fused in Glioblastoma) was also found in glioblastoma cell line." (PMID 26366867, 2015). "DBA identified a genomic breakpoint disrupting ROS1 in U-118MG cells, corresponding to the known GOPC/ROS1 (also called FIG/ROS1) gene fusion in this glioblastoma cell line." (PMID 23637631, 2013). "Chromosomal rearrangements involving the ROS1 gene were originally described in gioblastomas, where ROS1 (chromosome 6q22) is fused to the FIG (Fused in Glioblastoma) gene (chromosome 6q22 immediately adjacent to ROS1)." (PMID 22928112, 2012). "ROS1-rearrangements were first detected as FIG-ROS1 gene fusions in glioblastoma." (PMID 38347643, 2024). "In fact ROS1 fusion was first identified in glioblastoma multiforme in 1987." (PMID 37853341, 2023). "ROS1 rearrangements were most frequently seen in glioblastoma multiforme and breast cancer." (PMID 35233056, 2022). "A microdeletion in chromosome 6q21 is responsible for ROS-1 fusion with a new fused-in-glioblastoma gene that is responsible for ROS-1 overexpression and production of signals abnormally activating the tyrosine-kinase pathway, conferring its proto-oncogene role." (PMID 35200557, 2022).
glioblastoma (continued). "Moreover, we demonstrated that circENTPD7 acted as a sponge of miR-101-3p to regulate the expression of ROS1 further promoted the proliferation and motility of glioblastoma cells." (PMID 32308563, 2020). "The expression of miR-101-3p and ROS1 in glioblastoma tissues were examined by RT-qPCR." (PMID 32308563, 2020). "ROS1 fusion has been reported in glioblastoma multiforme, non-small cell lung cancer (NSCLC), cholangiocarcinoma, gastric cancer, and colorectal cancer, and NTRK fusion proteins have been reported in thyroid carcinoma, colorectal cancer, melanoma, breast cancer, and NSCLC." (PMID 29805770, 2018). "Despite the limited number of ROS1+ glioblastoma with OS survival information(N = 9), ROS1+ GBM patients had overall approximately 6 months (170 days) shorter OS while there was no major the differences between ROS1+ NSCLC versus non-ROS1+ NSCLC." (PMID 37853341, 2023). "Furthermore, miR-101-3p and ROS1 were also involved in glioblastoma cells growth and motility." (PMID 32308563, 2020). "Upon an oncogenic microdeletion, ROS1 fuses with fused-in-glioblastoma, leading to ROS1 overexpression and the activation of downstream signaling pathways." (PMID 40075878, 2025). "It has been introduced as a ROS1/ALK inhibitor in crizotinib-resistant ROS1-positive NSCLC and glioblastoma." (PMID 37568193, 2023). "This trial reports for the first time that the addition of crizotinib, an ALK, ROS1, and c-MET inhibitor, to standard RT and TMZ is safe and resulted in a promising efficacy for newly diagnosed patients with glioblastoma." (PMID 35625997, 2022). "In various cancers, including glioblastoma, melanoma, breast, lung, and prostate, tyrosine kinases are the most representative of these kinases, e.g., ALK, ROS1, RET, and FGFR." (PMID 35054873, 2022). "ROS1 gene rearrangements are observed in ~1–2% of NSCLC patients and in cholangiocarcinoma, glioblastoma, ovarian, gastric, and colorectal cancers." (PMID 31399568, 2019). "Next, we used a glioblastoma U-118 MG cell line, harboring the FIG-ROS1 fusion gene, and DS-6051b treatment dose dependently inhibited autophosphorylation of ROS1 in U-118-MG cells in vitro." (PMID 31399568, 2019). "ROS1 gene rearrangement was observed in around 1–2 % of NSCLC patients and in several other cancers such as cholangiocarcinoma, glioblastoma, or colorectal cancer." (PMID 31399568, 2019). "In this study we investigated ALK, ROS1, and MET status in nine glioblastoma stem cell lines and tumors from which they arise." (PMID 28960893, 2017). "The aim of this work was to study the targets of crizotinib: ALK, ROS1, and MET by using IHC, FISH, and direct sequencing in nine GSC lines derived from nine glioblastoma samples." (PMID 28960893, 2017). "Several ROS1 kinase fusion proteins have been identified, including the Fused in Glioblastoma–ROS1 (FIG–ROS) that was first discovered in a human glioblastoma cell line and more recently in patients with NSCLC, cholangiocarcinoma, and serous ovarian carcinoma." (PMID 25978031, 2015). "A literature review of these genes reported that ROS1 and GOPC are partners in an oncogenic fusion gene found in the glioblastoma cell line U118MG, created by a 240 kb intrachromosomal deletion." (PMID 22163003, 2011). "For example, unlike in glioblastomas, ROS1 gene fusion in NSCLC happens via interchromosomal translocations." (PMID 38629293, 2024). "Several ROS1 fusion genes have been identified in NSCLC, Spitz neoplasms, and glioblastomas." (PMID 38629293, 2024). "Although limited by the numbers of ROS1+ glioblastoma identified and thus statistically not significant, the presence of ROS1 fusions in glioblastoma seems to indicate a poor prognosis." (PMID 37853341, 2023). "ROS proto‐oncogene 1 (ROS1) is a RTK with an unknown physiological role in humans, while ROS1 fusion proteins drive occurrence of various tumors, including glioblastomas, NSCLC, and IMTs." (PMID 36254250, 2022).
glioblastoma (continued). "Unlike TRK-A, activation of ROS1 typically occurs when it is fused to oncogenic fusion partners such as fused in glioblastoma and solute carrier family 34 member 2 (SLC34A2)." (PMID 24386191, 2013).